CD4 (CD4 molecule)
Diseases named in the same sentence as CD4 in open-access papers (continued):
Sharing a sentence is not in itself a finding about the gene and the disease.
gout (22 papers, 2011 to 2026). A condition characterized by painful swelling of the joints, which is caused by deposition of urate crystals. "The same phenomenon was observed in our Uox-KO mice, suggesting a pathogenic role of this specific CD4+ T cell subset in gout occurrence and development." (PMID 35197978, 2022). "During the onset and resolution phases of gouty arthritis, a major hallmark of disease pathogenesis is the infiltration of immune cells, with mainly neutrophils and inflammatory monocytes in the early phases followed by CD4+ T cells in the latter." (PMID 34777378, 2021). "Specifically, 12 out of 28 immune cell subsets exhibited distinct variations, with activated CD4+ T cells, CD56dim natural killer cells, eosinophils, and T follicular helper cells, showing marked upregulation in gout patients." (PMID 40613560, 2025). "This aligns with our previous findings that QZTBD exerts its pharmacological effects against gout by modulating host amino acid metabolism and regulating CD4+ T cell differentiation." (PMID 40696369, 2025). "Some recent studies demonstrated that CD4+T cell subsets are also closely associated with gout, and indicated a significant factor of CD4+T cell subpopulations in gout." (PMID 38240927, 2024). "The correlation analysis of serum cytokine levels with circulating lymphocyte and CD4+T cell subpopulations in gout patients described that IL-2 levels were positively related to the absolute counts of Treg cells (rs = 0.283, p = 0.022)." (PMID 38240927, 2024). "Gout patients exhibit a natural enrichment of CD4 T cell subsets, with Th1 and Th17 immune cells confirmed to be involved in the onset of gout." (PMID 39432655, 2024). "The immune infiltration analysis showed that the expression of DEGs in gout was significantly upregulated in activated CD4 T cells, gamma delta T cells, T follicular helper cell, CD56dim natural killer cells, and eosinophil." (PMID 38368442, 2024). "Our analysis revealed some trends in the expression of homing receptors CCR5 and CCR7 as well as CD38 on CD4 T cells in gout patients indicating that the migratory pattern of T cells can be affected." (PMID 37714974, 2023). "The number of inferred interactions between naive CD4+ TCs and other myeloid cell subtypes increased during gout remission." (PMID 38063198, 2023). "KEGG analysis indicated that the DEGs of KLRB1+CD4+ TCs from gout remission were enriched for the FoxO signaling pathway." (PMID 38063198, 2023). "The IL-16 ligand and its CD4 receptor were also highly active during gout flares in CMs, myeloid cells, Tregs, and KLRB1+CD4+ TCs." (PMID 38063198, 2023). "In contrast, the DEGs of KLRB1+CD4+ TCs from the gout flare patient group only exhibited enrichment for the IL-17 signaling pathway." (PMID 38063198, 2023). "Increased frequency of CCR5+ CD4 T cells and reduced numbers of CCR7+ CD4 T cells in gout suggests an enhanced recruitment of these cells to inflamed tissues." (PMID 37714974, 2023). "We found that naïve CD4 T cells and classical monocytes cell populations were enriched in patients with gout, whereas plasmacytoid dendritic cells and intermediate monocytes were more abundant in healthy subjects." (PMID 36550178, 2022). "We found enriched naïve CD4 T cell and classical monocyte populations in patients with gout, and that the membranous markers of these cells are difficult to block using small molecules or antibodies." (PMID 36550178, 2022). "Our study shows that some specific T lymphocytes were changed in gout, including CD4+ T, Th2, Tfh1, Tfh2, Tc2, and Tc17, which suggests gout is associated with out-of-control growth of T lymphocytes." (PMID 33505406, 2020). "Overall, our study shows gout patients exhibit an overrepresentation of CD4+ T cells, Th2 cells, Tfh2 cells, and Tc2 cells and an underrepresentation of Tfh1 cells and Tc17 cells." (PMID 33505406, 2020).
gout (continued). "This study compared the peripheral lymphocyte and CD4+T cell subsets, and cytokines in gout and healthy controls (HCs) to explore the contributions of T helper 17 (Th17) cells, T regulatory (Treg) cells and cytokines to the pathogenesis of gout." (PMID 38240927, 2024). "Yet, the role of CD4+T cell subsets in gout process is poorly understood." (PMID 38240927, 2024). "Therefore, the aim of our study is to assess the lymphoid compartment in patients with CGD, FMF and gout, with a focus on innate-like unconventional gammadelta (γδ) T cells as well as CD4 and CD8 conventional alphabeta (αβ) T cells." (PMID 37714974, 2023). "Most blood immune cell subpopulations were similar between gout patients and healthy controls, with only naïve CD4 T cell, classic monocytes, intermediate monocytes, and pDCs being different between subject groups; the subclusters of these subpopulations also differed." (PMID 36550178, 2022). "Specifically, the proportion of myeloid cells in the Gout group was significantly higher than that in the NC group, while the proportions of CD4+ T cells, CD8+ T cells, and NK cells were significantly lower, suggesting that the imbalance in these cell populations may be a risk factor for gout." (PMID 40606658, 2025). "We subsequently identified DEGs in the CD4+ TCs, CD8+ TCs, and NK cell subtypes between gout flare and remission." (PMID 38063198, 2023). "In this study, we characterized three populations of blood lymphocytes: innate-like Vδ2, CD4, and CD8 T cells in CGD, FMF, and gout patients." (PMID 37714974, 2023). "We observed increased numbers of CCR5-expressing CD4 T cells and reduced numbers of CCR7-expressing CD4 and CD8 T cells in gout patients." (PMID 37714974, 2023). "The CD4+ TCs and CD8+ TCs from gout remission were enriched in chemokines, such as CXCR4, as well as various antiinflammatory regulators (TNFAIP3, ZFP36, and SMAD7; an antagonist of TGF-β signaling)." (PMID 38063198, 2023). "We therefore examined the expression profile of homing receptors to better understand the migratory status of Vδ2, CD4, and CD8 T cells in CGD, FMF, and gout." (PMID 37714974, 2023). "PMN-MDSCs were isolated from HCs or gout-derived-PBMCs by cell sorting and PMN-MDSCs (at a 1:1 ratio to the naïve CD4 T cells) were added to determine the role of MDSCs in regulating the polarization of T cells." (PMID 33154749, 2020). "Also, it proposed that the gut microbiota profoundly influences purine nucleotide catabolism and CD4+ Th17 cell infiltration by disrupting amino acid (AA) metabolism, in which CD4+ Th17 cells play an essential role in HUA and gout inflammation." (PMID 40161295, 2025). "In addition to a slight increase in the number of interactions involving MHC-II signaling during gout flares, we observed a distinct activation of the ligand HLA-DQA1 and its cognate receptor CD4." (PMID 38063198, 2023). "ORAI3 transcription was also increased in PsA, albeit not to the same extent as in RA, while the number of transcripts in naive CD4+ T cells from patients with SLE or gout were not different from those from HCs." (PMID 33568645, 2021). "Collectively, activation of CD4+iNKT cells promotes M2 polarization, which may contribute to iNKT cell-mediated protection from MSU crystal-induced gouty arthritis." (PMID 29312287, 2017). "This indicated that CD4+ TCs were likely not involved in the inflammatory response to gout." (PMID 38063198, 2023). "Our data strongly suggest that CD4+iNKT cells are one of the key regulators in the control of MSU crystal-induced gouty inflammation, and that iNKT cells may serve as a new therapeutic target for gout." (PMID 29312287, 2017).
idiopathic pulmonary fibrosis (22 papers, 2010 to 2026). Idiopathic pulmonary fibrosis (IPF) is a nonneoplastic pulmonary disease that is characterized by the formation of scar tissue within the lungs in the absence of any known cause. "Additionally, the ratio of Tim‐3+, ICOS+, and OX40+ in CD4+ T cells is significantly higher in patients with CT features of usual interstitial pneumonia compared with the non‐ILD group, which aligns with the findings of this study." (PMID 40165483, 2025). "PD-1+CD4+ T cells were found in three different fibrosis models, i.e., idiopathic pulmonary fibrosis (IPF), sarcoidosis, and bleomycin." (PMID 39502133, 2024). "A study which supports this idea showed that in patients with idiopathic pulmonary fibrosis (IPF), ANXA1 was associated with increased CD4+ T‐cell activity, as well as autoantibody production in patients with exacerbated IPF." (PMID 35146757, 2022). "CD4+ T cells infiltrates are more prominent in RA-IL than CD3+ T lymphocytes, in contrast with idiopathic pulmonary fibrosis (IPF) infiltrates." (PMID 35740390, 2022).
infarction (22 papers, 2013 to 2026). A localised pathological necrosis of tissue resulting from obstruction of the blood supply usually by a thrombus, an embolus, or vascular torsion. "Research has shown that CD4+ T cells are activated postmyocardial infarction to promote myocardial wound healing." (PMID 38548806, 2024). "It is well known that the number of CD4+CD25+Foxp3+ Tregs increases in the heart during the first day after infarction, indicating an antigen-independent migration of Tregs into the injured myocardium." (PMID 36066993, 2022). "We defined CD4+ AT2R+ cells as a T cell subset improving heart function post-MI corresponding with reduced infarction size in a rat MI-model." (PMID 25991381, 2015). "Considering that the activated CD4+ T cells could facilitate wound healing of the myocardium after AMI 36, it is reasonable to speculate that exosomes from DCs might activate CD4+ T cells to exert cardioprotective effects after infarction." (PMID 33391520, 2021). "Herein, we found that exosomes derived from activated CD4+ T cells (CD4-activated Exos) evoked pro-fibrotic effects of cardiac fibroblasts, and their delivery into the heart aggravated cardiac fibrosis and dysfunction post-infarction." (PMID 32327611, 2020). "In our analysis, serum Troponin I levels at 7 days post-infarction showed a positive correlation with CD4 + IFNγ+ lymphocytes, suggesting that patients with a high percentage of CD4 + IFNγ+ lymphocytes at 1 h post-infarction may have higher circulating Troponin I levels at 7 days." (PMID 30898123, 2019). "CD4+ and CD8+ T-cell subsets showed distinct, location-dependent dynamics: cortical infarction induced earlier modulation of memory and regulatory phenotypes, whereas subcortical infarction produced slower but more persistent shifts." (PMID 41676150, 2026). "Flowcytometric analysis of Tie2-CreERT2;Wt1lox/lox+Tamoxifen hearts in the acute phase after infarction revealed on average a nine-fold reduction of MDSC numbers as compared to controls and doubled lymphocyte invasion (including CD3, CD4, and CD8 lymphocytes)." (PMID 40585983, 2025). "CD4 count positively correlated with ART exposure (r = 0.762; p = 0.030), infarctions (r = 0.633; p = 0.049), left hemiplegia (r = 0.866; p = 0.015), and gastroenteritis (r = 0.612; p = 0.045)." (PMID 38745940, 2024). "Given that the frequency of anti-inflammatory CD4+ Foxp3+ Tregs among all CD4+ T cells in heart-draining lymph nodes has been demonstrated to increase as early as 3 days after MI, it is speculated that DC-derived exosomes might activate cardioprotective Tregs after infarction." (PMID 30984201, 2019). "The analysis showed a strong positive correlation between the percentage of CD4+ IFNγ+ T cells 1 h after AMI and the levels of Troponin I at 7 days post-infarction (r = 0.7847; p = 0.0367)." (PMID 30898123, 2019). "Links between neuronal cell survival and CCR3 have been described: Ccr3-expressing CD4+ T cells are necessary for facial motoneuron survival after facial nerve axotomy, whereas CCR3 promotes neuronal cell death in a post-infarction mouse model." (PMID 29186205, 2017). "Notably, the proportion of P2X7-positive cells was significantly elevated in both CD4+ and CD8+T cells during both the acute phase (3 days) and subacute stage (7 days) post-infarction in the brain." (PMID 40948793, 2025). "Regarding the role of the NF-kB signalling pathway, we hypothesized that its participation in the pathogenesis of AMI may also be related to CD4-expressing T cells, TNF-α and IL-10 in myocardial ischaemia and infarction." (PMID 32332808, 2020). "In this study, CD4+ AT2R+ were shown for the first time to act as a ‘regulatory’ T cell subset facilitating cardiac regeneration, as evident from improved cardiac function and reduced infarction size." (PMID 25991381, 2015).
infarction (continued). "The absence of CD4 + T cells leads to an increase in monocyte count in infarcted myocardial cells, suggesting that CD4 + T cell infiltration into the myocardial infarct site may induce pro-inflammatory monocyte differentiation." (PMID 37268894, 2023). "Conversely, diminished concentrations of CD3, CD4, and INF-γ demonstrate negative correlations with lacunar infarction (CD3: P = 0.004, χ2 = 8.184; CD4: P = 0.009, χ2 = 6.396; INF-γ: P = 0.003, χ2 = 13.132)." (PMID 38287458, 2024).
infectious mononucleosis (22 papers, 2011 to 2025). A condition characterized by an increase in mononuclear white blood cells and swollen lymph nodes, which is usually caused by infection with the Epstein-Barr virus. "A reduction in circulating CD4+CD25+ Tregs was previously reported in infectious mononucleosis patients, indicating that low Tregs accentuates the acute effector T-cell response to EBV." (PMID 41332545, 2025). "In humans, CD4+ CTLs from infectious mononucleosis patients or CMV-infected individuals have been shown to express Tbx21, Granzymes, and NKG7, as we have demonstrated." (PMID 36077655, 2022). "The studies of adolescents with infectious mononucleosis predominantly generated EBV-specific CD4+ TEM and TCM responses, consistent with our findings that the quality of EBV-specific T cell immunity is dependent on age." (PMID 34771539, 2021). "It is also worth to note that patients with PTA or HY featured reproducible increases in the numbers of CD4(+) helper T-cells in the periphery, reminiscent of lymphocytosis described for cases of PTA associated to infectious mononucleosis." (PMID 28877231, 2017). "Even during infectious mononucleosis, circulating granzyme B+ CD4+ T cell are detected in the blood, and in sharp contrast with the CD8+ T cell compartment, their number does not correlate with symptom severity, thus suggesting a potential protective role." (PMID 28289418, 2017). "While EBV gp350-specific CD8 T cells have been detected in patients during infectious mononucleosis and gp350-specific CD4 T cells have been detected in healthy EBV carriers, the level of these T cells has not been quantified relative to those against EBNA-3." (PMID 22028652, 2011). "Our data suggest that the gH/gL-ferritin vaccine may effectively engage CD4+ T cell subsets, which is particularly important for preventing infectious mononucleosis, where overly polarized Th1 responses can exacerbate immunopathology." (PMID 40573345, 2025). "The fact that EBV-positive infectious mononucleosis patients have a significant increase in IL-17A-producing CD4+ T cells for at least a month following symptoms supports the idea that gammaherpesviruses that lack an IL-17A homologue usurp host IL-17A signaling to promote infection." (PMID 33824206, 2021). "In support of this hypothesis, EBV-positive infectious mononucleosis patients display a significant increase in IL-17A-producing CD4+ T cells, an increase that persists at least 1 month following the resolution of clinical symptoms." (PMID 33824206, 2021). "The fact that NIL-specific CD4+ T-cells efficiently recognise newly infected B-cells, are present and activated during infectious mononucleosis yet are unable to prevent the virus establishing permanent infection of the host raises the question of whether they would ever be protective." (PMID 34882759, 2021). "For instance, in children with infectious mononucleosis, treatment with pidotimod resulted in decreased numbers of CD3+ and CD8+ cells, alongside increased levels of CD4+ cells and elevated CD4+/CD8+ ratios." (PMID 40691766, 2025). "In humans, CD4+ CTLs rarely exist in circulating T cells; however, EBV-specific CD4+ CTLs were detected in the peripheral blood of patients who recovered from infectious mononucleosis." (PMID 36077655, 2022). "CD8 + cells exhibit more clonal expansions upon antigen stimulus than CD4 + cells and especially large clonal expansions of CD8 cells have been demonstrated in infectious mononucleosis." (PMID 27932211, 2017). "BHGZD significantly ameliorates infectious mononucleosis via decreasing the levels of CD3+, CD8+, aspartate aminotransferase (AST), lactic dehydrogenase (LDH), creatine (9CK), and isoenzyme (CK-MB) and increasing the levels of CD4+, CD4+/CD8+, and IgA and IgG." (PMID 34675809, 2021).
infectious mononucleosis (continued). "Although it has been established in the literature that numbers of CD4+ T cells are not substantially increased during infectious mononucleosis, data exist to support the concept that CD4+ T cells are important contributors to the control of EBV." (PMID 25774295, 2015). "This inability to proliferate results in a lower viral load, and indicates that the reason MHV68 does not induce a fatal infectious mononucleosis in these mice is because the virus is unable to efficiently drive B cell proliferation in vivo in the absence of CD4 help." (PMID 24789087, 2014).